HMGB2 (high mobility group box 2)
Diseases named in the same sentence as HMGB2 in open-access papers (continued):
Sharing a sentence is not in itself a finding about the gene and the disease.
cervical cancer (7 papers, 2020 to 2025). A primary or metastatic malignant neoplasm involving the cervix. "Moreover, further research results showed that HMGB2 was frequently up-regulated in cervical cancer samples and its up-regulation was associated with primary tumor size, infiltration depth and FIGO stage, resulting in tumor progression." (PMID 33407071, 2021). "The up-regulated HMGB2 was discovered to be associated with human cervical cancer." (PMID 33407071, 2021). "Here, we reported that the up-regulated HMGB2 was associated with human cervical cancer." (PMID 33407071, 2021). "Although the exactly underlying mechanism of HMGB in prognosis of patients with cervical cancer remained uncovered, our results revealed that HMGB2 might at least partly promote cervical cancer progression and it might be a potentially prognostic biomarker for cervical cancer patients." (PMID 33407071, 2021). "In cervical cancer cell lines (SiHa and HeLa), HMGB2 knockdown significantly impaired cell invasion." (PMID 40396172, 2025). "In cervical cancer cells, SiHa and HeLa, HMGB2 knockdown followed by Palbociclib treatment also led to a significant reduction in the percentage of EdU-positive cells." (PMID 40396172, 2025). "In conclusion, circRNA THBS1 silencing inhibited the malignant biological behaviors of cervical cancer cells via the regulation of miR-543/HMGB2 axis." (PMID 37465349, 2023). "The findings indicated that knockdown of circRNA THBS1 inhibited the malignant biological behavior of cervical cancer cells by miR-543/HMGB2 axis." (PMID 37465349, 2023). "Overall, the expression of HMGB2 in cervical cancer samples was significantly higher than in HSIL and normal cervical samples (both P < 0.05)." (PMID 33407071, 2021). "Here, our findings indicated that high expression of HMGB2 was significantly associated with primary tumor size, invasion (infiltration depth) and FIGO stage in cervical cancer." (PMID 33407071, 2021). "In cervical cancer cell lines (SiHa and HeLa), HMGB2 knockdown markedly impaired migration ability." (PMID 40396172, 2025). "Additionally, further studies revealed that HMGB2 was commonly up-regulated in cervical cancer samples and that this up-regulation was related to the size, depth, and FIGO stage of the initial tumor, resulting in tumor progression." (PMID 38328436, 2023). "Strong HMGB2 immunoreactivity (20/29) was found in cervical cancer tissues." (PMID 33407071, 2021). "Therefore, we detected the expression of HMGB2 in cervical cancer tissues by immunohistochemistry and evaluated the significance of HMGB2 expression in the clinical further." (PMID 33407071, 2021). "Interestingly, positive reaction of HMGB2 was gradually higher during the progression of cervical cancer." (PMID 33407071, 2021). "However, the expression and function of HMGB2, especially its relevance in carcinogenesis in cervical cancer remains largely unknown." (PMID 33407071, 2021). "circRNA THBS1 silencing inhibited cervical cancer cell proliferation and EMT and induced cell apoptosis via the regulation of miR-543/HMGB2 axis, suggesting its carcinogenic role in cervical cancer." (PMID 37465349, 2023). "Our findings strongly showed that circRNA THBS1 regulates cervical cancer cell proliferation, apoptosis, and EMT via regulating miR-543/HMGB2 axis." (PMID 37465349, 2023). "Of 29 cervical cancer samples, 9 (35.5%) samples with IRS of 0-1 were classified as low HMGB2 expression (HMGB2-low), and 20 (64.5%) samples with IRS of 2-3 were classified as high HMGB2 expression (HMGB2-high)." (PMID 33407071, 2021). "suggest that HMGB2 may promote cell proliferation by activating the AKT signaling pathway, thus making it a promising candidate in the search for new biomarkers and therapeutic targets in cervical cancer." (PMID 36568211, 2022).
bladder cancer (6 papers, 2013 to 2022). "Considering the positive correlation between TUG1 and HMGB2 expression in bladder cancer tissues and cells, as well as their consistent change under radiation treatment, we assumed that TUG1 may affect the radiosensitivity of bladder cancer cells via regulating the expression of HMGB2." (PMID 28376901, 2017). "However, the clinicopathological significance of HMGB1 and HMGB2 expression in bladder carcinoma (BCa), particularly the involvement of these proteins in angiogenesis, remains unclear." (PMID 23426143, 2013). "HMGB1 and HMGB2 are the main members of the HMGB protein family and their overexpression has been observed in numerous human malignancies, including hepatocellular, skin squamous cell, prostate, gastrointestinal breast, and bladder carcinomas." (PMID 24479488, 2014).
pancreatic cancer (6 papers, 2019 to 2025). "HMGB2 was reported to play a role in several cancers, including colorectal carcinoma, gastric, and pancreatic cancer." (PMID 34651416, 2021).
cardiac hypertrophy (5 papers, 2013 to 2026). "miR-23b-5p, which we predicted to target Acad8, is also known to target Hmgb2 and thereby play a role in cardiac hypertrophy." (PMID 37167320, 2023). "The abnormal overexpression of miR-23b-5p promotes cardiac hypertrophy and dysfunction via HMGB2, and aberrant expression of miR-127-5p impairs the function of granulosa cells via HMGB2 in premature ovarian insufficiency." (PMID 35159393, 2022). "Histological and echocardiographic analysis at P28 showed that HMGB2 overexpression did not significantly affect cardiac function or induce pathological cardiac hypertrophy." (PMID 41092376, 2026).
colorectal cancer (5 papers, 2021 to 2025). A primary or metastatic malignant neoplasm that affects the colon or rectum. "Research studies have shown that HMGB1 and HMGB2 are closely related to colorectal cancer and can be used as potential diagnostic and prognostic markers." (PMID 35712661, 2022). "Here, HMGB2 blockade represents a promising strategy to increase the curative efficiency of the anti–PD-1 therapy in both HCC and colorectal cancer, attributed to augmented IFN-γ+ CD8+ T cell infiltration." (PMID 40315321, 2025). "High expression of HMGB2 in CD8+ T cells indicated treatment resistance to immunotherapy in both HCC and colorectal cancers." (PMID 40315321, 2025). "CDK1, HMGB2, SSRP1, and H2AFV may serve as key nodes for HMGB1 in colorectal cancer." (PMID 36230798, 2022). "In addition, CDK1, HMGB2, SSRP1, and H2AFV may serve as key nodes for HMGB1 in colorectal cancer." (PMID 36230798, 2022).
COVID-19 (5 papers, 2021 to 2025). A disease caused by infection with severe acute respiratory syndrome coronavirus 2. "Concurrently, using the ADT information of the COVID-19 data set, the original authors discovered a cell cluster that contains S100A8/9/12hi HMGB2-expressing monocytes and found that patients with a larger proportion of cells coming from this cluster exhibited increased illness severity." (PMID 41256547, 2025). "In addition, we found that some TFs were differentially expressed in severe COVID-19, including TF upregulations of IRF7, SP100, HMGB2, and BCL6, and downregulations of FOS and JUNB." (PMID 38612651, 2024). "We were unable to find similar studies on the role of HMGB2; however, due to the high structural homology of HMGB1 and HMGB2 proteins, the possible role of the latter one in the course/development of COVID-19 cannot be completely ruled out." (PMID 37176041, 2023).
glioblastoma (5 papers, 2015 to 2024). The most malignant astrocytic tumor (WHO grade IV). "Public data showed that HMGB2 mRNA expression was significantly higher in the “cellular tumor”, than in the surrounding infiltrative areas, and that proneural glioblastomas (which are usually associated with IDH mutations) had higher HMGB2 expression than mesenchymal and classical glioblastomas." (PMID 38672598, 2024). "When glioblastoma specific promoter (HMGB2) was used to control Herpex simplex thymidine kinase (tk), targeted glioblastoma expression was detected in mouse xenograft model." (PMID 25912715, 2015). "In glioblastomas, high HMGB2 expression identified tumors with better response to the standard treatment and could be used as additional inclusion/exclusion criterion to enroll patients in future clinical trials of new treatments." (PMID 38672598, 2024).
lung cancer (5 papers, 2021 to 2025). A malignant neoplasm involving the lung. "In lung cancer samples, the mRNA expression levels of HMGB2 were slightly elevated, and HMGB3 was significantly up-regulated in cancer tissue vs. normal tissues in multiple datasets." (PMID 35923467, 2022). "All these results indicated that the HMGB2 might play an important role in the development of tumors, including lung cancer." (PMID 35962344, 2022).
myocardial infarction (5 papers, 2019 to 2026). Gross necrosis of the myocardium, as a result of interruption of the blood supply to the area, as in coronary thrombosis. "Besides HMGB1, HMGB2 is associated with myocardial infarction severity and induces cell apoptosis in myocardial ischemic animals." (PMID 30886640, 2019). "Previous studies have showed that the expression level of HMGB2 was increased in the serum of myocardial infarction patients and has a positive correlation with myocardial infarction severity and cellular apoptosis." (PMID 35966335, 2022). "Study has shown that both HMGB1 and HMGB2 levels increase in the serum of myocardial infarction patients, ischemic myocardial tissues, and hypoxic H9C2 cells." (PMID 30886640, 2019). "It has been known that increased HMGB2 levels were related to major adverse cardiac events and negatively with ejection fraction in myocardial infarction patients." (PMID 30886640, 2019). "Previous clinical studies have demonstrated thatelevated HMGB2 expression correlates with the severity of myocardial infarction(MI), major adverse cardiovascular events (MACEs) at one month, and in-stentrestenosis." (PMID 40776964, 2025).
myocardial ischemia (4 papers, 2021 to 2023). A disorder of cardiac function caused by insufficient blood flow to the muscle tissue of the heart. "According to the previous studies, HMGB2-accelerated myocardial ischemia injury through ROS-mediated apoptosis, abnormal autophagy, and inflammatory response." (PMID 38148870, 2023). "miRNA-130a-5p suppresses myocardial ischemia reperfusion injury by downregulating the HMGB2/NF-κB axis." (PMID 35159393, 2022).
osteoarthritis (4 papers, 2021 to 2023). A noninflammatory degenerative joint disease occurring chiefly in older persons, characterized by degeneration of the articular cartilage, hypertrophy of bone at the margins and changes in the synovial membrane. "Aging-related loss of HMGB2 in articular cartilage is linked to reduced cellularity, which contributes to the development of osteoarthritis." (PMID 35159393, 2022). "Moreover, aging-related loss of HMGB2 induces osteoarthritis and reduces cellularity in humans." (PMID 36539852, 2022). "It was showed that HMGB2 knockout mice exhibited severe osteoarthritis, and their fertility decreased, which was due to Sertoli and degeneration of germ cell in immotile spermatozoa and seminiferous tubules." (PMID 34215724, 2021). "We therefore consider these approaches, including the study of osteoarthritis development in surgical and aging models, as the next steps in our quest to understand the role of NDRG2, WSB1, JMJD6, TSPYL2, HMGB2 and PPP1R15A in osteoarthritis and their inner mechanistic links." (PMID 37033917, 2023).
prostate carcinoma (4 papers, 2019 to 2024). A carcinoma that arises from epithelial cells of the prostate gland. "In prostate cancer, the early detection of HMGB2 in prostate tissues using IHC contributed to the early-stage diagnosis of prostate cancer." (PMID 35962344, 2022). "We have carried out the first HMGB1/HMGB2 interactome approach in prostate cancer (PCa) using both the PC-3 cell line and adenocarcinoma tissue." (PMID 31694235, 2019). "In summary, YY1 is a recognized prostate cancer driver and different complexes in which YY1 takes part can induce activation or repression of gene expression, including also AR-YY1-mediated PSA transcription, which we found is also regulated by HMGB1 and HMGB2 silencing." (PMID 31694235, 2019).
skin cancer (4 papers, 2013 to 2025). "Notably, HMGB2, a recently identified nuclear compression-induced EMT driver in a skin cancer model – remained unchanged under both mechanical and chemical stimulation, suggesting that this pathway depends on the extreme nuclear deformation by very stiff tumor environments like skin cancer." (PMID 41415449, 2025).
viral infection (4 papers, 2020 to 2024). "Studies have identified HMGB2 as a crucial regulator of CD8+ T cell exhaustion during chronic viral infection and cancer, critical for their long-term maintenance." (PMID 39247201, 2024). "We infected wild-type (WT) mice with either LCMV Armstrong (Arm) or Clone 13 (Cl13) to induce an acute or chronic viral infection, respectively, and measured HMGB2 levels in MHC class I tetramer+ virus-specific CD8+ T cells." (PMID 37704621, 2023). "Here the authors show that High-Mobility Group Box 2 (HMGB2) protein promotes CD8+ T cell memory cell generation in acute viral infection and exhaustion stemness in chronic infection." (PMID 37704621, 2023). "After acute viral infection, we observe a decrease of Hmgb2−/− CD8+ memory T cells, with defective central memory T cell (Tcm) formation and recall capacity." (PMID 37704621, 2023). "In response to chronic viral infection, exhausted Hmgb2−/− CD8+ T cells showed decreased progenitor exhausted T cell (Tpex) differentiation and survival, with these cells unable to persist during prolonged infection." (PMID 37704621, 2023). "Accordingly, both WT and Hmgb2−/− P14 T cells expanded to similar numbers by 8dpi Cl13 infection, indicating that Hmgb2−/− P14 T cells were effectively primed and activated during early stages of chronic viral infection." (PMID 37704621, 2023). "In the setting of acute viral infection, Hmgb2−/− memory CD8+ T cells developed, but they were defective in their differentiation and recall capacity." (PMID 37704621, 2023). "During acute viral infection, we found an important role for HMGB2 in memory T cell differentiation of MPEC and Tcm phenotypes, and memory recall responses." (PMID 37704621, 2023). "In summary, we show that Hmgb2 expression is required for the differentiation and survival of memory and Tpex cells during acute and chronic viral infection, respectively." (PMID 37704621, 2023). "Previous research has shown that Cynoglossus semilaevis HMGB2 possesses immunoregulatory properties that promote resistance against bacterial and viral infection." (PMID 33178199, 2020). "In response to chronic viral infection, Hmgb2−/− CD8+ T cells show decreased Tpex differentiation." (PMID 37704621, 2023). "Together, these findings showed that HMGB2 regulated the survival and differentiation of memory CD8+ T cells during acute viral infection." (PMID 37704621, 2023). "Furthermore, HMGB2 also had a cell-intrinsic function in the differentiation and function of memory CD8+ T cells after acute viral infection." (PMID 37704621, 2023). "Since we found Hmgb2−/− CD8+ T cells were significantly decreased during acute and chronic viral infection, we next assessed whether there were differences in their proliferation and/or survival." (PMID 37704621, 2023).
abdominal aortic aneurysm (3 papers, 2023 to 2025). Enlargement and ballooning of the vessel that supplies arterial blood to the abdomen, pelvis and legs. "Our work focused on the mechanism by which HMGB2 regulate ferroptosis and inflammation in abdominal aortic aneurysm (AAA)." (PMID 38148870, 2023).
liver fibrosis (3 papers, 2021 to 2025). "HMGB2 is involved in stellate cell activation, and serum HMGB2 levels are increased in patients with liver fibrosis and cirrhosis." (PMID 40269686, 2025). "Notably, the evidence suggesting that blood levels of HMGB2 may serve as diagnostic markers for early-stage liver fibrosis and cirrhosis underscores its potential role in the early development of HCC, providing a window for preventive interventions aimed at mitigating disease progression." (PMID 39247201, 2024).
lung adenocarcinoma (3 papers, 2022). A carcinoma that arises from the lung and is characterized by the presence of malignant glandular epithelial cells. "Moreover, HMGB2 serves as a potential prognostic biomarker and therapeutic target for lung adenocarcinoma (LUAD)." (PMID 35962344, 2022). "Thus, we intended to investigate the potential role of HMGB2-derived circRNAs in lung adenocarcinomas (LUAD) and squamous cell carcinomas (LUSC)." (PMID 35525959, 2022).
retinoblastoma (3 papers, 2019 to 2024). A malignant tumor that originates in the nuclear layer of the retina. "Lately, HMGB2 has been found to overexpress and promote cell proliferation and radiosensitivity through retinoblastoma-interaction-dependent or independent mechanisms." (PMID 33407071, 2021). "PAK2 plays a role in apoptosis and activation of Rac, while HMGB2 is participating in chromatin regulation and retinoblastoma in cancer." (PMID 30988666, 2019).
atherosclerosis (2 papers, 2023 to 2025). A disease characterized by the build-up of fatty material and calcium deposition in the arterial wall resulting in partial or complete occlusion of the arterial lumen. "Moreover, HMGB2 has recently been identified as a key driver of several vascular diseases, including atherosclerosis and coronary artery in-stent restenosis." (PMID 38148870, 2023).
diabetes (2 papers, 2021 to 2025). "The increased serum concentration of beta-2 microglobulin (B2M) is used as a clinical marker for diabetes mellitus, and high-mobility group protein B2 (HMGB2) is used as a diagnostic marker for both obese and diabetic patients." (PMID 34561612, 2021). "Following adjustment for age, smoking history, hypertension, hyperlipidemia,statin use and diabetes, the serum levels of HMGB1 (OR: 1.212, 95% CI:1.003–1.465, p < 0.05) and HMGB2 (OR: 1.117, 95% CI: 1.005–1.241,p < 0.05) were independently associated with AAA rupture." (PMID 40776964, 2025). "Compared to the control group, the AAA groupexhibited significantly higher levels of current smoking history, hypertension,HMGB1, HMGB2, TnI, NT-pro BNP, and D-Dimer (p < 0.05), while showinglower levels of never smoked, statin use, diabetes, sTREM-1, eGFR, TG, TC, andHbA1c (p < 0.05)." (PMID 40776964, 2025).
IgA nephropathy (2 papers, 2019 to 2022). "miRNA-127 controls embryonic stem cell pluripotency via the HMGB2-OCT/SOX2 axis, and miR-590-3p contributes to the severity of IgA nephropathy via downregulation of HMGB2 in peripheral mononuclear cells." (PMID 35159393, 2022).
influenza (2 papers, 2013 to 2023). An acute viral infection of the respiratory tract, occurring in isolated cases, in epidemics, or in pandemics; it is caused by serologically different strains of viruses (influenzaviruses) designated A, B, and C, has a 3-day incubation period, and usually lasts for 3 to 10 days. "While influenza cases were primarily characterized by pro-inflammatory signaling and classical anti-viral response gene expression (e.g., BCL6, DLL4, GDF15, PTX3,HMGB2, and IL-8)." (PMID 36371548, 2023).
injury (2 papers, 2021 to 2025). Damage inflicted on the body as the direct or indirect result of an external force, with or without disruption of structural continuity. "Traumatic brain injury induces HMGB2 expression in a subset of reactive astrocytes." (PMID 40247387, 2025).